H3C3 (H3 clustered histone 3)
Description:
Core component of nucleosome. Nucleosomes wrap and compact DNA into chromatin, limiting DNA accessibility to the cellular machineries which require DNA as a template. Histones thereby play a central role in transcription regulation, DNA repair, DNA replication and chromosomal stability. DNA accessibility is regulated via a complex set of post-translational modifications of histones, also called histone code, and nucleosome remodeling.
Synonyms: H3/c; H3.1; H3FC; HIST1H3C
Gene: Protein-coding gene on chromosome 6 (26,045,384 to 26,045,869, forward strand). Ensembl gene ENSG00000287080.
Subcellular location: Nucleus; Chromosome
Subcellular location (Human Protein Atlas): Nucleoplasm
Pathways (Reactome):
Gene expression (Transcription): B-WICH complex positively regulates rRNA expression; DNA methylation; ERCC6 (CSB) and EHMT2 (G9a) positively regulate rRNA expression; MLL4 and MLL3 complexes regulate expression of PPARG target genes in adipogenesis and hepatic steatosis; NoRC negatively regulates rRNA expression; PRC2 methylates histones and DNA; RNA Polymerase I Promoter Escape; RNA Polymerase I Promoter Opening; RUNX1 regulates genes involved in megakaryocyte differentiation and platelet function; RUNX1 regulates transcription of genes involved in differentiation of HSCs; Regulation of endogenous retroelements by KRAB-ZFP proteins; Regulation of endogenous retroelements by Piwi-interacting RNAs (piRNAs); Regulation of endogenous retroelements by the Human Silencing Hub (HUSH) complex; SIRT1 negatively regulates rRNA expression; Transcriptional regulation by small RNAs
Chromatin organization: CHD1 and CHD2 subfamily; CHD6, CHD7, CHD8, CHD9 subfamily; ChAHP complex assembly; Chromatin modifying enzymes; HATs acetylate histones; HDACs deacetylate histones; HDMs demethylate histones; Interaction of NuRD complexes with transcription factors; NuRD complex assembly; PKMTs methylate histone lysines; RMTs methylate histone arginines
Disease: Defective pyroptosis; Dengue Virus-Host Interactions; HCMV Early Events; HCMV Late Events
Signal Transduction: Activated PKN1 stimulates transcription of AR (androgen receptor) regulated genes KLK2 and KLK3; Estrogen-dependent gene expression; Formation of the beta-catenin:TCF transactivating complex; Pre-NOTCH Transcription and Translation
Developmental Biology: Activation of anterior HOX genes in hindbrain development during early embryogenesis; Chromatin modifications during the maternal to zygotic transition (MZT); Transcriptional regulation of granulopoiesis
Immune System: FXIIa activates plasma kallikrein-kinin system; Interleukin-7 signaling; Regulation of PD-L1(CD274) transcription
and 8 more pathways
Gene Ontology:
Molecular function: cadherin binding; protein binding; structural constituent of chromatin; nucleosomal DNA binding; DNA binding; protein heterodimerization activity
Biological process: epigenetic regulation of gene expression; nucleosome assembly; chromatin organization; heterochromatin formation; telomere organization
Cellular component: chromatin; extracellular exosome; membrane; nucleoplasm; nucleosome; nucleus; protein-containing complex; extracellular region; chromosome
Genetic constraint (gnomAD): Loss-of-function variants: 14 observed, 8.34 expected, observed/expected ratio (o/e) 1.68, 90% interval 1.05 to 1.95. That is too few expected variants to judge how well the gene tolerates losing a copy. Missense variants: 205 observed, 207.24 expected, observed/expected ratio (o/e) 0.99, 90% interval 0.88 to 1.11. Synonymous variants: 178 observed, 83.43 expected, observed/expected ratio (o/e) 2.13.
Homologues: Orthologues: Drosophila melanogaster His3:CG33812 (99% identical), zebrafish si:ch1073-153i20.2 (99% identical), zebrafish si:ch211-113a14.20 (99% identical), zebrafish si:ch211-113a14.23 (99% identical), zebrafish si:ch211-113a14.27 (99% identical), zebrafish zgc:173552 (99% identical), Caenorhabditis elegans his-17 (97% identical), Caenorhabditis elegans his-2 (97% identical), Caenorhabditis elegans his-32 (97% identical), Caenorhabditis elegans his-40 (97% identical), Caenorhabditis elegans his-42 (97% identical), Caenorhabditis elegans his-45 (97% identical), and 5 more. Paralogues in human: H3C1 (100% identical), H3C10 (100% identical), H3C11 (100% identical), H3C12 (100% identical), H3C2 (100% identical), H3C4 (100% identical), H3C6 (100% identical), H3C7 (100% identical), H3C8 (100% identical), H3C13 (99% identical), H3C14 (99% identical), H3C15 (99% identical), and 8 more.
Diseases named in the same sentence as H3C3 in open-access papers:
H3C3 is named in the same sentence as 5 diseases in open-access papers, as found by Europe PMC text mining. Sharing a sentence is not in itself a finding about the gene and the disease.
H3C3 shares sentences with these, for which no sentence is quoted: asthma (1 paper); brain tumours (1); cancer (1); pulmonary TB (1); tumor (1).